CD28 (CD28 molecule)
Diseases named in the same sentence as CD28 in open-access papers (continued):
Sharing a sentence is not in itself a finding about the gene and the disease.
melanoma (continued). "In our study neither the occurrence of anti-nuclear antibodies (ANA) nor thyreoglobulin antibodies (TG-abs) was associated with prolonged PFS or OS, nor did we found a correlation between occurrence of ANA or TG abs and the occurrence of CD28 abs in our melanoma patients." (PMID 23483974, 2013). "Furthermore, neither the type of primary melanoma (p = 0.211) nor its Clark Level (p = 0.240) correlated with the presence of CD28 abs, while 52% of the patients with CD28 abs had a primary melanoma with a depth of penetration according to Clark Level IV or V." (PMID 23483974, 2013). "Presence of CD28 was correlated with a higher risk of dying from melanoma (p = 0.043), but not with a significantly shortened overall survival or progression-free survival." (PMID 23483974, 2013). "A competition assay using mouse monoclonal abs and purified human CD28 abs could further prove the direct inhibitory effect of human CD28 abs derived from melanoma patients on the CD28 receptor of Jurkat cells." (PMID 23483974, 2013). "Moreover, LPPC/MP/CD28 complexes could eliminate metastatic B16F10 melanoma cells in the lung more efficiently than LPPC/MP." (PMID 36691089, 2023). "Hence, combining melanoma antigen-specific TCRs with CD2::CD28 chimeric receptors might have potential in adoptive T cell therapy, since melanoma cells were shown to have high expression of CD58." (PMID 29707134, 2018). "Therefore, PD1 and CD28 expression by T-Exo may be a valuable tool in predicting the best responders to immunotherapy among patients with melanoma, while CD80 and CD86 levels may serve as prognostic biomarkers." (PMID 29755693, 2018). "Hence, if IFN really abets the generation of CD28 abs, and the latter cause immune suppressive effects by stimulation of T regs or blocking of the CD28 receptor in its proper function, the continuation of IFN-therapies should be critically reconsidered in melanoma patients who develop CD28 abs." (PMID 23483974, 2013). "B16 melanoma cells were transfected with ssRNAs expressing co-stimulatory molecules and then co-cultured with splenocytes in the presence of anti-CD3/CD28 antibodies." (PMID 41541266, 2026). "After validating the functionality of the scFv RB4 fragment (affinity, specificity and recognition of ETB+ melanoma cell lines), it was inserted into a second-generation CAR structure with a CD8 hinge and CD28 and CD3z as stimulation domains." (PMID 41222596, 2025). "CD8+ T cells were isolated from the peripheral blood mononuclear cells (PBMCs) of 16 melanoma patients and activated with CD3/CD28/IL-2 stimulation, with CD45+/CD3+/CD8+ cells identified as the CD8+ T-cell population." (PMID 40860143, 2025). "Since both genes are co-located on chromosome 2 q33.2, are members of the CD28 immune checkpoint receptor family, are co-expressed in melanomas from the TCGA cohort, we expected co-expression of ICOS and CTLA4 in melanoma cell lines as well." (PMID 37259155, 2023). "Initially, we observed a significantly increased percentage of FOXP3+ Tregs in melanoma patient compared to healthy volunteer peripheral blood, following anti-CD3/CD28 activation." (PMID 35909944, 2022). "After C57BL/6 mice were challenged with freshly prepared B16-F10 (B16) melanoma cells or vehicle controls (PBS), the expression of ICOS, ICOSL and CD28 in the lung was assessed 2 weeks later." (PMID 36618349, 2022). "Studies showed an increase in CD8 + CD28- T cells expressing the CD161 receptor in melanoma diseases, indicating that CD8 + CD28- T cells can be activated in these patients." (PMID 36660546, 2022). "Poly(I:C) ameliorated melanoma- inhibition of ICOS, ICOSL and CD28 while abrogating the ability of B16 cells to stimulate CTLA-4." (PMID 36618349, 2022). "Here we demonstrate that CHI3L1 inhibits the expression of ICOS, ICOSL and CD28 while stimulating CTLA-4 and the B7 moieties in melanoma lung metastasis." (PMID 36618349, 2022).
melanoma (continued). "Regarding their therapeutic effect, G2 PD-L1-targeting 4-1BB-inserted CAR-T cells had superior anti-tumor activity over CD28- and GITR-incorporated CAR-T cells in mouse models of melanoma and lymphoma." (PMID 35053463, 2022). "Through protein expression scanning by the Human Protein Atlas, overexpression of FLI1, CD28, CD80, and IL21R was discovered in melanoma." (PMID 33971970, 2021). "Gene expression analysis revealed top pathways (T cell trafficking, communication, and differentiation) and top upstream regulators (CD3, CD28, IFNG, and STAT3) that significantly changed with age in 84 IMCG and 43 TCGA primary melanomas." (PMID 27760559, 2016). "Enhancing CD28 co-stimulatory signals alongside PD1 inhibition may amplify T cell-mediated antitumor effects, as demonstrated in melanoma models." (PMID 40136325, 2025). "To examine B7H6 as a potential target for CAR T therapy to AML and melanoma, we thus developed two different second-generation CAR constructs composed of the extracellular domain of the NCR NKp30 and either CD28 or CD137 as costimulatory domains fused to the CD3ζ signaling moiety." (PMID 40943160, 2025). "In the study reported here, we have tested the effect of the CCL21+ICAM1 SIN, on the expansion and cytotoxic phenotype of Tumor Infiltrating Lymphocytes (TIL) from melanoma patients, following activation with immobilized anti-CD3/CD28 stimulation, or commercial activation beads." (PMID 36937426, 2023). "Moreover, compared to the co-stimulatory CAR-T domains DAP-10, CD28, 4-1BB, ICOS, and OX40, GITR co-stimulation exhibited stronger cytotoxicity in vivo in T cell lymphoma and melanoma models." (PMID 35053463, 2022). "ICOS, a T-cell costimulatory molecule of the CTLA-4/PD-1/CD28 family, plays a nonoverlapping function with CD28 and is highly expressed by TA-Tregs in breast carcinoma, ovarian carcinoma, follicular lymphoma, melanoma, RCC and gastric cancer." (PMID 33924428, 2021). "A similar study using a PD-1:CD28 CSR construct showed that its co-expression is equally beneficial for CD4+ and CD8+ T cells, and can improve the functional avidity of TCRs targeting tyrosinase in xenograft models of human melanoma." (PMID 32570906, 2020). "To verify that the up-regulation of PD-L1 in tumor cells is a direct effect of the IFNγ present in the TME, we treated SM1 melanoma cells in vitro with NextA or vehicle control and then co-cultured with CD3/CD28 activated splenocytes in the presence of anti-PD1 antibody." (PMID 30992475, 2019). "In-vitro PFC-labeled ovalbumin (OVA)-specific T cells from the T cell receptor-transgenic line OT-1, activated with anti-CD3 and anti-CD28 antibodies (Tact) or OVA-peptide pulsed antigen presenting cells (TOVA-act), were injected into B16 OVA melanoma-bearing mice." (PMID 27736925, 2016). "Sera taken from healthy persons or sera from melanoma patients without CD28 autoantibodies did not have an inhibitory effect." (PMID 23483974, 2013). "Melanoma TIL consists mostly of activated TCRαβ+ CD4+ and CD8+ T cells with heterogeneous phenotypes ranging from less differentiated effector-memory cells to more differentiated cells that have lost critical co-stimulatory molecules, such as CD27 and CD28." (PMID 23560068, 2013). "In contrast to sera derived from healthy persons or from melanoma patients without CD28 autoantibodies, CD28 autoantibody containing sera showed an inhibitory effect on Jurkat cell stimulation." (PMID 23483974, 2013). "We demonstrated that polyfunctional cytotoxic CD8+ T cells specific for the HIV-associated SL9 or melanoma-associated MART-1 epitopes were expanded by αCD28-Immuno-STAT delivering peptide-specific TCR and CD28 signals, but not peptide-specific TCR signals alone." (PMID 40762498, 2025).
melanoma (continued). "Our group recently demonstrated that the high levels of CD28 and PD-1 exposed by Exo correlate with the therapeutic response to anti-CTLA4 immunotherapy in metastatic melanoma, whereas those from DCs reflect the restoration of immune system activity against melanoma cells." (PMID 29755693, 2018). "To determine the effects of local CpG or CpG + GM administration on T cell skewing in the melanoma SLN, we measured Th1 and Th2 cytokines in supernatants of freshly isolated SLN cells ex vivo, which were stimulated overnight by immobilized anti-CD3 and anti-CD28." (PMID 26935057, 2016). "Purified CD4+ T cells were stimulated with beads coated with anti-CD3 and anti-CD28 antibodies and co-transduced with a lentivirus expressing codon-optimized CD8α and individual CD8β isoforms and a second lentivirus expressing TCRαβ from a CD8 dependent TCR recognizing the melanoma antigen NY-ESO-1." (PMID 23533620, 2013). "Therefore, the possibility must be considered that CD28 abs lead to a worse response to IFN treatment by hampering IFN signalling, although in our study occurrence of CD28 abs did not correlate with response to IFN therapy in melanoma or hepatitis patients." (PMID 23483974, 2013). "To analyze whether IL-27-mediated PD-L1 induction on melanoma cells could have an immunosuppressive effect, we performed co-culture experiments in which A375 cells were pre-treated or not with IL-27 for 15 hrs before incubation with PBMC and CD3/CD28 beads for 3 days." (PMID 24130734, 2013). "Herein, starting from the analysis of a panel of Ag-specific melanoma CD8+PD1+ T-cell clones, we have identified different transcriptomic, phenotypic, and functional patterns dictated by the presence/absence of CD28 in peripheral and matched NSCLC tissue." (PMID 37898752, 2023). "Unlike CD4+ and CD8+ T cells observed in melanoma patients, T cells observed in breast tumors showed differential expression of the CD27 cell surface marker, where only half of the CD28+ cells were also positive for cell-surface CD27." (PMID 31417550, 2019). "To test the possibility that melanoma cell lines inhibited T cell proliferation through ADO production, we evaluated the proliferation of CD4+ and CD8+ T cells activated by anti-CD3/anti-CD28 beads in the presence or absence of primary melanoma cells." (PMID 26329660, 2015). "Given the lack of CD40 costimulatory molecule expression by melanomas, the ligation of CD86 or CD80 with T cell CD28 molecules may be even more critical." (PMID 35162988, 2022).
Autoimmunity (71 papers, 2009 to 2025). The occurrence of an immune reaction against the organism's own cells or tissues. "The blockade of CD28 signalling is known to reduce pathological T cell responses in the context of both autoimmunity and transplantation, but has been associated with impairment of the regulatory T cell compartment." (PMID 36347877, 2022). "IL-2 promotes Tregs and knockout of IL-2 or IL-2-receptor causes lethal autoimmunity, therefore CD28 drives a more regulatory environment while CD40 promotes an inflammatory environment." (PMID 28192476, 2017). "Furthermore, CD28, which was linked to autoimmunity in 64 peer-reviewed articles, was strongly interconnected in the PPI network." (PMID 37488170, 2023). "Because CD28 is the main co-stimulatory molecule for the activation of T cells, we wanted to investigate its impact on the course of the virus infection as well as on a potential development of autoimmunity as seen in susceptible mouse strains for TMEV." (PMID 37090733, 2023). "Abatacept inhibits the CD80/CD86:CD28 costimulatory signal required for full T cell activation and as such may alter the immune responses to tumors, as well as dampening pathogenic autoimmunity." (PMID 31703717, 2019). "The intrinsic CD28 deficiency in peripheral Treg resulted in autoimmunity that could be prevented by supplementation with CD28-sufficient Treg20." (PMID 28223693, 2017). "An epigenetically altered CD4+CD28+ T cell subset, caused at least in part by nitration of T cell signaling molecules, is found in patients with active lupus, and nitrated T cells are sufficient to cause lupus-like autoimmunity in animal models." (PMID 28620656, 2017). "Our data suggest a positive effect of CD28+DN T cells on autoimmunity, in line with a previous study in which these cells were described to have a regulatory function in non‐obese diabetic mouse (NOD) model." (PMID 39835539, 2025). "Therapeutic targeting of ligands by CTLA4-Ig fusion proteins (Abatacept) or blocking CTLA4 with antibodies (e.g. Ipilimumab) have been used in autoimmunity and cancer to inhibit or invigorate CD28 signals, respectively." (PMID 40496752, 2025). "Our data suggest a positive effect of CD28+ subpopulations in protecting from autoimmunity, indeed CD28 co‐stimulation provides a proper T cell activation promoting cell cycle entry and the production of various cytokines." (PMID 39835539, 2025). "Experimental studies indicate that CD28 conditional knockout results in severe autoimmunity and inappropriate resolution of allergy, suggesting that CD28 plays post-maturational roles in Tregs." (PMID 38755605, 2024). "Altogether these data support a pathogenic role of CD28+ CD27- TEMRA and EM CD4+ T cells in autoimmunity." (PMID 35185762, 2022). "Understanding the requirements for CD28 costimulation during immune responses is important for many therapeutic approaches including immune suppression in autoimmunity and transplantation, as well as cancer immunotherapy." (PMID 33223527, 2020). "Conversely, CD28 antagonists designed as CTLA-4-Ig fusion proteins are effective at ameliorating symptoms in autoimmune disorders and at preventing transplant rejection." (PMID 32665635, 2020). "Our findings are also consistent with the fact that CTLA-4 and PD1 blockade, both of which increase CD28 signals, are known to trigger autoimmunity." (PMID 33223527, 2020). "CD28 is a differentiation antigen expressed on T cells and plays a role in Treg-mediated autoimmunity control." (PMID 33585004, 2020). "In this review, we discuss the role of CD28 in tolerance and autoimmunity and the clinical efficacy of drugs that block or enhance CD28 signaling, by highlighting the success and failure of pre-clinical studies, when translated to humans." (PMID 29904580, 2018).
Autoimmunity (continued). "CTLA-4 has a higher binding affinity for B-7 ligands than CD28, and CTLA-4 can bind to B7 and displace CD28, leading to attenuation and termination of T cell responses and establishment of tolerance, to minimize the development of autoimmunity." (PMID 28545567, 2017). "Given the potential prominence of CD28 signaling, considered crucial for T cell activation, it was assumed that CD28 would be a useful target for controlling autoimmunity." (PMID 28878738, 2017). "Here, we review the available proof of concept studies for CD28 antagonists in autoimmunity, with a special focus on the mechanisms of action." (PMID 31548534, 2017). "To understand how the lack of Gal-8 predisposes the immune system to a more pronounced CNS autoimmunity we compared lymphocyte subpopulations and the responses of spleen cells to ex vivo anti-CD3/anti-CD28 activation and to re-stimulation with MOGp." (PMID 28650992, 2017). "The data reviewed above in the field of autoimmunity show a strong consensus for anti-CD28 blockade, which is similar to transplantation models, with a disturbed generation of effector T cells and expansion of regulatory mechanisms (Treg cells, IDO)." (PMID 31548534, 2017). "Tregs from CD28-ΔTreg mice displayed reduced suppressive capacity, and consequently CD28-ΔTreg animals developed spontaneous autoimmunity." (PMID 26870040, 2016). "How regulation through the CD28 axis is altered in settings of autoimmunity is therefore an important area of study." (PMID 26134669, 2015). "Studies have shown that genetic defects in CTLA-4 lead to CD28-mediated severe autoimmunity." (PMID 38695984, 2024). "However, knockout of CD28 or blockade of CD28 with specific antibodies prevents the development of autoimmunity such as experimental autoimmune encephalitis (EAE) in rodents, and rhesus monkeys or collagen-induced arthritis." (PMID 37090733, 2023). "Here, we review available preclinical experience with “antagonist only” anti-CD28 antibodies in autoimmunity models and discuss what clinical benefit might be obtained from this novel therapeutic approach in the corresponding human pathologies." (PMID 31548534, 2017). "Given its functional importance in the initiation of T cell expansion and differentiation, CD28 has been an attractive target for therapeutic intervention, and blockers of the CD28 pathway are now approved for use in autoimmunity (abatacept) and transplantation (belatacept)." (PMID 26098894, 2015). "Nonetheless, since CD28 engagement alters the Th17/Th1 ratio toward Th1, under some circumstances it may aggravate autoimmunity." (PMID 19333372, 2009). "Thus, Treg-αζDKO not only completely or partially reversed defects in Tregs, Tfr, and GC B-cells and humoral immunity caused by CD28 deficiency but also triggered IgG1-predominant autoimmunity independent of CD28." (PMID 39651265, 2025). "Thus, frequencies of cytotoxic CD8+CD28− T cells in the blood are increased across CTDs, raising the possibility that these cells may be responsible for perpetuating autoimmunity and mediating tissue damage upon migration to local disease sites." (PMID 36232733, 2022). "Since the initial report, approximately two decades ago, that engagement of CD28 enhances glycolysis but PD-1 and CTLA-4 decrease it, significant information has been generated which has linked metabolic reprogramming with the fate of differentiating T cell in health and autoimmunity." (PMID 32257420, 2020). "Studies have suggested that CD28 may play a role following T cell priming, for example blocking CD28 ligands during an ongoing immune response can impair the germinal center response, prolong graft survival, and suppress autoimmunity." (PMID 25347065, 2014). "The CD28–CTLA-4 pathway is an integrated system for regulating T cell activation and preventing autoimmunity, based on the balance of four competing interactions with both stimulatory and inhibitory outcomes." (PMID 35999394, 2022).